GDF15 (growth differentiation factor 15)
Diseases named in the same sentence as GDF15 in open-access papers (continued):
Sharing a sentence is not in itself a finding about the gene and the disease.
dementia (continued). "(2016) demonstrated that higher levels of GDF15 may be a biomarker for incognitive impairment no dementia (CICD) and AD in individual with white matter hyperintensities." (PMID 35068064, 2022). "First, several circulating protein markers potentially relevant to dementia, for example, GFAP and GDF-15, were not assayed in ELSA." (PMID 40092369, 2025). "Another study on GDF-15 levels in atypical parkinsonian syndromes showed that cerebrospinal fluid GDF-15 levels in patients with Lewy body dementia were significantly higher than those in patients with PD and dementia but lower than those in patients with PD without dementia." (PMID 37755357, 2023).
thalassemia (27 papers, 2010 to 2025). An inherited blood disorder characterized by a decreased synthesis of one of the polypeptide chains that form hemoglobin. "Fourth, the striking reduction in frequency of NVP in women with thalassaemia, a condition of markedly increased prepregnancy levels of GDF15, suggests that GDF15 plays a key role in the causation of these symptoms in pregnancy." (PMID 38092039, 2024). "Conversely, high levels of GDF15 preceding pregnancy, as are found in thalassaemia, are associated with a reduction in the prevalence of NVP." (PMID 38092039, 2024). "We did not register an association between the annual blood transfusion volume and GDF15 levels among all patients with thalassaemia." (PMID 36806122, 2023). "The transcription factor GDF15 level is found elevated mainly in patients with ineffective erythropoiesis (e.g., thalassemia) causing hepcidin level downregulation in these cases." (PMID 31067791, 2019). "GDF-15 is known to be implicated in dyserythropoietic syndromes such as thalassemia or sickle cell disease." (PMID 25171167, 2014). "In thalassemia, GDF15 protein, which is the result of mutations in such patients, works as the inhibitor of peptide-Hepcidin hormone and sends it's reducing signal to the liver." (PMID 24757621, 2013). "However, in quadratic models adjusted for sex and age, GDF15 concentrations were associated with BMI in both the All Thalassaemia and the Thalassaemia Major groups." (PMID 36806122, 2023). "Hepcidin deficiency which is mediated by GDF15 overexpression arising from an expanded erythroid compartment probably contributes to iron overload in thalassemia patients by inhibiting hepcidin expression and subsequently participates in tissue iron overloading in these patients." (PMID 30834265, 2019). "The levels of GDF15 are increased in thalassemia, produced by erythroid progenitors, resulting in a decreased hepcidin secretion from the liver." (PMID 40421055, 2025). "In patients with thalassemia, the high levels of growth differentiation factor 15 (GDF15) and erythroferrin can also inhibit the production of hepcidin." (PMID 39931654, 2025). "In a study of patients with thalassemia intermedia, GDF15 levels correlated with cardiovascular disease; and in patients with pneumonia, GDF15 effectively predicted the degree of myocardial damage." (PMID 40019842, 2025). "GDF15 levels were markedly elevated in thalassaemia patients (24.2‐fold with β‐thalassaemia major compared with healthy controls)." (PMID 36806122, 2023). "It is therefore notable that we did see a relationship between GDF15 and BMI in the context of thalassaemia that would be consistent with the known effects of GDF15 to reduce energy stores." (PMID 36806122, 2023). "After adjustment for BMI, age and Tanner stage, serum IGF1 concentrations correlated negatively with GDF15 in all thalassaemia patients (β = −.027, p = .02)." (PMID 36806122, 2023). "The levels of GDF15 were substantially elevated in patients with β‐thalassaemia when compared to non‐thalassaemia controls (p = 3.9 × 10−11) and heterozygous carriers of β‐thalassaemia trait (p = 1.4 × 10−7)." (PMID 36806122, 2023). "IGF1 concentration showed significant inverse correlations with GDF15 concentration (adjusted for BMI, age, sex and Tanner stage) in both the All Thalassaemia and the Thalassaemia Major groups." (PMID 36806122, 2023). "Patients with thalassaemia have previously been reported to have extremely high levels of GDF15, which is believed to be derived from their expanded mass of abnormal red cell precursors." (PMID 36806122, 2023). "We have undertaken studies in patients with thalassaemia to examine the relationship between levels of GDF15, anthropometric variables and endocrine parameters." (PMID 36806122, 2023). "Very high GDF15 levels are found in thalassaemia, where growth, energy balance and neuroendocrine function are impaired." (PMID 36806122, 2023).
thalassemia (continued). "The authors went on to demonstrate that GDF15 was markedly upregulated in both α and β-thalassemia—with mean values in β-thalassemia of 66 000 pg/ml, which is among the highest levels seen in any human disease." (PMID 32310257, 2020). "The first study to examine GDF15 in the thalassemias was prompted to do so by findings demonstrating markedly increased GDF15 expression in erythroblasts as an in vitro model of erythropoiesis." (PMID 32310257, 2020). "In thalassemia, ineffective erythropoiesis induces the release of factors including GDF15, twisted gastrulation protein homolog 1 (TWSG1), hypoxia-inducible factor (HIF), and ERFE, which can all inhibit hepcidin release." (PMID 30834265, 2019). "Again in this study, in human hepatocyte cultures, serum GDF15 and recombinant GDF15 in patients with thalassemia were shown to suppress hepcidin production." (PMID 30761871, 2019). "According to researchers at the NIH, iron overload in patients with thalassemia can be due to an overproduction of a protein called GDF15." (PMID 28428807, 2016). "On treating primary human hepatocytes or HuH7 cells with high concentrations of GDF15 (similar to those found in patients with thalassaemia) hepcidin transcription was inhibited." (PMID 26182354, 2015). "In thalassaemia, overexpression of the erythropoietic factor, growth differentiation factor 15 (GDF15) contributes to iron overload by inhibiting hepcidin expression, and thereby increasing iron absorption through the gut." (PMID 25265971, 2014). "GDF15, a marker of ineffective erythropoiesis in humans with thalassemia, was significantly increased in the culture supernatants from the beta-KD cells." (PMID 23861885, 2013). "GDF15, a marker of erythroblast apoptosis that is usually increased in the serum of patients with thalassemia, was also increased in the culture supernatants of the beta-KD cells." (PMID 23861885, 2013). "Growth differentiation factor 15 (GDF15) has been demonstrated to suppress hepcidin expression and is elevated in patients with thalassemia." (PMID 21912548, 2011). "But other factors as overexpression of the growth and differentiation factor (GDF-15) which inhibits the production of hepcidin in the liver have been discussed as possible contributors to excess body iron in thalassemia." (PMID 21687645, 2011). "Serum from thalassemia patients suppressed hepcidin mRNA expression in primary human hepatocytes and depletion of GDF15 reversed the hepcidin suppression." (PMID 20827391, 2010). "In cultured human hepatocytes and hepatic cell lines, both recombinant GDF15 as well as GDF15 in the serum of thalassemia patients inhibited the expression of hepcidin." (PMID 20467559, 2010). "Also, thalassemia patients had significantly higher levels of GDF15 and ERFE and lower hepcidin levels than controls (P value < 0.001)." (PMID 37464096, 2023). "All cells can increase GDF15 secretion when stressed and it is possible that non haematopoietic compartments make some contribution to the high GDF15 levels in thalassaemia, which to date has been reported to be a marker of ineffective erythropoiesis and an indicator of disease severity." (PMID 36806122, 2023). "A marked elevation of circulating GDF15 in thalassemia have been confirmed several times." (PMID 32310257, 2020). "Growth differentiation factor 15 (Gdf15), twisted gastrulation 1 (Twsg1) and erythroferrone (Erfe) which are produced by erythroid precursors have been proposed to be potential candidates for hepcidin regulator under such conditions including thalassemia." (PMID 32219031, 2020). "In conclusion we are increasingly convinced of the importance to study the molecular mechanisms of iron homeostasis dysregulation in thalassemia and in particular the GDF15-BMP-Hepcidin-Ferroportin regulatory way in order to understand its contribution to iron overload." (PMID 20827391, 2010). "Hepcidin suppression in thalassemia may be mediated in part by growth differentiation factor 15 (GDF-15)." (PMID 20490352, 2010).
thalassemia (continued). "Recent observations in thalassemia patients has suggested that one of these regulators could be the cytokine growth differentiation factor-15 (GDF15)." (PMID 20827391, 2010). "Our results suggest that GDF15 may play a role in influencing the low adiposity and low IGF1 seen in thalassaemia." (PMID 36806122, 2023). "Plasma growth differentiation factor-15 (GDF15) levels, which are elevated in thalassemia major and inhibit hepdcidin synthesis, did not appear to negatively regulate hepcidin in this setting, consistent with results in normal volunteers treated with low-dose recombinant human erythropoietin." (PMID 20368776, 2010).
chronic heart failure (26 papers, 2012 to 2025). "GDF15 is inversely correlated with body mass index (BMI) in patients with chronic heart failure in keeping with a pathogenic role in cardiac cachexia." (PMID 32310257, 2020). "GDF-15 are also associated to impairment of diastolic function in patients with chronic heart failure and conditions of severe disease in patients with hypertrophic cardiomyopathy (HCM), which indicated that GDF15 and may influence different processes in cardiac remodeling." (PMID 23071585, 2012). "Studies have shown a predictive role of GDF-15 across an array of CVD including chronic heart failure." (PMID 40317389, 2025). "GDF15 is a stress response cytokine that is elevated in various chronic diseases such as cancer cachexia and chronic heart failure, and GDF15 levels are positively correlated with inflammatory markers." (PMID 40119457, 2025). "In univariate analysis in patients with chronic heart failure, GDF-15 was related to creatinine, erythrocyte count, hemoglobin, hepcidin, and total iron-binding capacity and tended to correlate with EF." (PMID 27043030, 2016). "In multivariate analysis, hepcidin, creatinine, and EF were found to be predictors of GDF-15 in chronic heart failure." (PMID 27043030, 2016). "GDF-15 could be a valuable biomarker for monitoring children with congenital heart disease and congestive heart failure, helping assess disease severity and guide treatment." (PMID 40149646, 2025). "Studies have shifted focus toward novel biomarkers, such as soluble suppression of tumorigenicity 2 (sST2), high-sensitivity troponin, and growth differentiation factor 15 (GDF-15), which show promising prognostic capabilities in both acute and chronic heart failure settings." (PMID 40297163, 2025). "The aim of this study was to determine whether growth differentiation factor-15 (GDF-15) and circulating neprilysin (cNEP) improve the diagnosis of congestive heart failure (HF) in patients on dialysis." (PMID 32002632, 2020). "To investigate whether the levels of GDF-15 are similarly elevated as NT-proBNP by concomitant AF in patients with HF, we performed a post hoc analysis of these two biomarkers in The BIOlogy Study to Tailored Treatment in Chronic Heart Failure (BIOSTAT-CHF)." (PMID 31263996, 2020). "Moreover, clinical trials have shown that GDF-15 can be regarded as a reliable biomarker of CVD, and chronic heart failure." (PMID 31581569, 2019). "A recent report characterized measurements of NT-proBNP, ST2, GDF-15, and hs-TnT in the cohort from the PROTECT (ProBNP Outpatient Tailored Chronic Heart Failure) study, which accounted for HF admissions as time-to-first event but not recurrent hospitalizations." (PMID 27777932, 2016). "Indeed, several studies have also reported higher plasma GDF-15 levels in patients with cardiovascular pathologies such as CAD, ACS or chronic heart failure." (PMID 25171167, 2014).
diabetic nephropathy (25 papers, 2013 to 2026). "GDF-15 has also been associated with diabetic kidney disease in T1D and has shown a correlation with eGFR." (PMID 39000435, 2024). "Enhanced GDF15 levels correlate not only with increased mortality in hemodialysis and diabetic nephropathy (DN) patients but also with all-cause mortality." (PMID 32977372, 2020). "To conclude, our results suggest that not only diabetic kidney disease but also other neurovascular complications are associated with the concentration of GDF-15." (PMID 31936869, 2020). "Additionally, a higher GDF-15 level was associated with diabetic kidney disease, peripheral neuropathy, and proliferative retinopathy vs. nonproliferative retinopathy." (PMID 31936869, 2020). "Moreover, higher GDF-15 concentration was an independent predictor of kidney function deterioration and all-cause mortality in patients with diabetic kidney disease." (PMID 31936869, 2020). "Interestingly, elevated urinary excretion of GDF15 is associated with proximal tubular injury, a clear determinant of tubulo-interstitial inflammation and fibrosis in diabetic nephropathy." (PMID 23457584, 2013). "Besides the relation between GDF-15 and diabetic kidney disease, it may be also associated with peripheral neuropathy and retinopathy." (PMID 31936869, 2020). "Growth differentiation factor 15 (GDF-15), a homeostatic cytokine, also plays a protective role in diabetic nephropathy." (PMID 41302503, 2025). "The AGE/RAGE axis, one of the GDF-15-related signaling pathways identified in the present study, was inhibited by increased expression of GDF-15, which has also been found to inhibit renal inflammation in patients with diabetic nephropathy." (PMID 39420932, 2024). "In conclusion, this study has shown promising results regarding MMP-3 and GDF-15 as biomarkers for diabetic nephropathy and neuropathy." (PMID 39000435, 2024). "While this study did not investigate diabetic retinopathy in particular, we indeed demonstrate that circulating GDF15 is elevated in subjects with diabetic nephropathy and is positively correlated with urine ACR and negatively correlated with eGFR." (PMID 35683420, 2022). "Regarding diabetic complications, several reports have demonstrated the role of serum GDF15 in diabetic nephropathy and have suggested that GDF15 is a predictor of diabetic kidney disease." (PMID 35683420, 2022). "As to diabetic complications, previous studies have demonstrated that serum GDF15 concentrations are related to cardiovascular disease and diabetic nephropathy and retinopathy, indicating its potential role as a novel biomarker." (PMID 35683420, 2022). "In our study, GDF-15 turned out to be a statistically significant marker of diabetic kidney disease occurrence." (PMID 31936869, 2020). "Studies in healthy males and in adults with diabetic nephropathy have shown a faster decline of GFR in patients with high levels of GDF-15." (PMID 32089755, 2020). "In this study, patients with diabetic kidney disease had higher GDF-15 concentrations, similarly to our patients." (PMID 31936869, 2020). "GDF-15 has also been suggested to predict decline of renal function in diabetic nephropathy." (PMID 39000435, 2024). "Interestingly, urinary GDF15 levels predict renal function decline in diabetic kidney disease patients, independently of plasma GDF15 levels." (PMID 38892145, 2024). "For instance, FGF1 has been previously shown to inhibit the NF-κB pathway in experimental diabetic nephropathy, whereas GDF15–mediated inhibition of NF-κB signalling reduces infiltration of macrophages and arrests the pro-apoptotic activity in early tumour development." (PMID 35883655, 2022). "Notably, three protein‐coding genes (Upk1b, Psca and Gdf15) and two lncRNAs (NONMMUG023520.2 and NONMMUG032975.2) were identified to be Smad3‐dependent and to be associated with the development of diabetic nephropathy." (PMID 33369170, 2021).
diabetic nephropathy (continued). "However, it was correlated with GDF-15 concentrations, which are related to diabetic kidney disease, so it can be a reflection of such evidence." (PMID 31936869, 2020). "Besides its role in heart diseases, there are preliminary studies concerning the role of GDF-15 in diabetic kidney disease development." (PMID 31936869, 2020). "In multivariate logistic regression analysis, increasing GDF-15 turned out to be a statistically significant independent predictor of the prevalence of diabetic kidney disease (OR: 1.07; 95% CI: 1.01–1.12; p = 0.015) after an adjustment for T1DM duration, HbA1c, BMI, and smoking (p = 0.0002)." (PMID 31936869, 2020). "In fact, GDF-15 is expressed in the collecting ducts in the kidney and there are publications that associate GDF-15 with kidney dysfunction in mice and in some pathologies such as diabetic nephropathy and in patients undergoing coronary artery bypass grafting." (PMID 26867126, 2016). "In contrast, some lines of evidence point to a protective role of GDF-15 in diabetic nephropathy." (PMID 27717384, 2016). "In addition, GDF-15 levels were higher in patients with diabetic nephropathy than in diabetic patients without diabetic nephropathy and were associated with impaired kidney function." (PMID 38672115, 2024). "The results strongly indicate that in T1DM, serum EGF concentration might serve as a useful marker to detect microangiopathy, while GDF-15 may probably be engaged to some extent in microvascular damage as a marker of diabetic kidney disease, peripheral neuropathy, and retinopathy." (PMID 31936869, 2020). "We assessed the causal effect of cystatin C together with other five serum biomarkers including KIM-1, GDF-15, TBIL, uric acid, and Scr on diabetic nephropathy by Mendelian randomization (MR) analysis." (PMID 36482996, 2022). "GDF-15 is an important potential biomarker for RF; combined therapy of acupuncture and oral Chinese medicine can reduce GDF-15 levels and improve renal function in patients with early diabetic nephropathy." (PMID 41566544, 2026). "The protective effect was also observed in mouse models of diabetic nephropathy, which indicated that renal and systemic inflammation, the AGE/RAGE axis and its downstream inflammatory and adhesion molecules were significantly inhibited when GDF-15 was overexpressed." (PMID 40371061, 2025).